NOX4 (NADPH oxidase 4)
Diseases named in the same sentence as NOX4 in open-access papers (continued):
Sharing a sentence is not in itself a finding about the gene and the disease.
ischemic stroke (continued). "Based on data from different NOX knockout mouse models in ischemic stroke, the most relevant isoform appears to be NOX4." (PMID 22625431, 2012). "We also determined the functional outcome and mortality of 6- to 8-wk-old male Nox4−/− mice and matched wild-type controls over a longer time period after ischemic stroke." (PMID 20877715, 2010). "Our data suggest that NOX4-mediated oxidative stress leads to neuronal damage via leakage of the blood–brain barrier and neuronal apoptosis—two pathophysiological hallmarks of ischemic stroke." (PMID 20877715, 2010). "Furthermore, the study also examined the expression levels of NOX4, a marker of oxidative stress with a crucial role in the development of ischemic stroke." (PMID 39334724, 2024). "The expression of NOX4 plays a key regulatory role in the development of ischemic stroke." (PMID 35154560, 2022). "In this section, we will further discuss the role of NOX4 in the pathogenesis of ischemic stroke." (PMID 35154560, 2022). "Blockade of NOX4-mediated ROS production and signal transduction pathways may help to improve the prognosis of patients with ischemic stroke." (PMID 35154560, 2022). "The role of NOX4 in ischemic stroke is attracting an increasing level of interest." (PMID 35154560, 2022). "NOX4 is a promising therapeutic target for treating ischemic stroke." (PMID 35154560, 2022). "NOX4 is also a promising therapeutic target for the treatment of ischemic stroke." (PMID 35154560, 2022). "G-Rb1 was also shown to downregulate NOX4 expression and activity in ischemic stroke." (PMID 35154560, 2022). "Further, the major source of NOX4 is endothelial cells in ischemic stroke." (PMID 35154560, 2022). "It is known that induction of ischemic stroke leads to elevated CNS expression of NOX4." (PMID 33869275, 2021). "VAS2870 has been reported to decrease Nox4-derived ROS, involved in ischemic stroke induction." (PMID 32751795, 2020). "However, recent studies have found that the expression of NOX4 is increased after acute brain injury, including ischemic stroke and traumatic brain injury." (PMID 33281556, 2020). "In addition, recent researches demonstrated that NOX4 exerted the protective effect against blood-brain barrier breakdown, oxidative stress, and neuronal apoptosis during ischemic stroke." (PMID 31827699, 2019). "In the meantime, the breakdown of BBB, the special structure that differentiates the brain from the heart and other organs, could be attributed to the ROS produced by the endothelial NOX4 during ischemic stroke." (PMID 31827699, 2019). "Ischemic stroke induces NOX4 activated, and previous research revealed that inhibition of NOX4 could suppress the enhanced level of MMP-9 induced by tMCAO." (PMID 28690765, 2017). "NOX4 has also been confirmed to increase in the brain after ischemic stroke." (PMID 26941888, 2016). "Also, in vivo data suggest that VAS2870 does inhibit NOX4 in native systems: in a mouse ischemic stroke model, we observed the same protective effect of VAS2870 in the wild-type as by deletion of NOX4." (PMID 22648375, 2012). "In an interesting study using NOX1, NOX2 and NOX4 deficient mice as well as the specific NOX Inhibitor VAS2870, the pathophysiological role of the different NOX isoforms in ischemic stroke has now been assessed in terms of infarct development and blood-brain-barrier damage." (PMID 20356357, 2010). "In addition, we discuss therapeutic strategies targeting NOX4 for treating ischemic stroke." (PMID 35154560, 2022). "Guhong injection could significantly suppress NOX4 expression in the treatment of ischemic stroke." (PMID 35154560, 2022). "Therefore, preventing the generation of ROS early in the process by blocking NOX4 might be a potential therapeutic strategy for treatment of ischemic stroke." (PMID 26952102, 2016). "Therefore, NOX4 could be considered a prominent therapeutic target in ischemic stroke." (PMID 35853974, 2022).
ischemic stroke (continued). "Several drugs targeting NOX4, such as SCM-198, Iso, G-Rb1, betulinic acid, and electroacupuncture, have shown efficacy as treatments of ischemic stroke." (PMID 35154560, 2022). "During ischemic stroke NOX2, NOX3, and NOX4 isotypes modulates their expression depending on cell type and time post-injury." (PMID 33869275, 2021). "Nox4/ROS plays key regulatory roles during oxidative stress process, for example, Nox4 belongs to the NADPH oxidase family member, which plays a major role in the pathological process of ROS production and neurodegeneration in ischemic stroke." (PMID 31379960, 2019). "In general, these data indicate that NOX2, NOX4, and DUOX1 expression increase after ischemic stroke." (PMID 26941888, 2016).
Sepsis (30 papers, 2014 to 2026). Sepsis is defined as life-threatening organ dysfunction caused by a dysregulated host response to infection. "In conclusion, echinacoside attenuated sepsis-induced lung oxidative stress in mice, and this effect may be associated with the NOX4-Nrf2 axis." (PMID 38001778, 2023). "Prior studies have suggested that inhibition of Nox4 reduced oxidative stress and lung injury caused by various diseases or conditions such as sepsis, ischemia-reperfusion, influenza A virus infection and paraquat poisoning, suggesting Nox4 inhibition exerts protective effects against lung injury." (PMID 36120334, 2022). "Studies have shown that the genetic or pharmacological inhibition of NOX4 suppresses ROS production and activates the NF-κB signaling pathway, thereby alleviating sepsis-induced AKI." (PMID 40722880, 2025). "NOX4 was identified as a positive regulator of ferroptosis in 20 hearts sourced from patients who died from sepsis (GSE79962 from the GEO database) compared to 11 control hearts from non-failed donors." (PMID 41009041, 2025). "Shikonin, a naphthoquinone from Lithospermum erythrorhizon roots, reduces oxidative stress by inhibiting NOX2 and NOX4 enzymes activities and expression in doxorubicin-induced cardiotoxicity, and sepsis-induced acute kidney injury animal models respectively." (PMID 40520207, 2025). "NOX4, as the major source of reactive oxygen species, was upregulated in sepsis to induce oxidative stress and inflammation." (PMID 40698661, 2025). "In a mouse model of LPS-induced sepsis-induced lung injury, reducing TRIM27 was found to alleviate sepsis-induced inflammation, oxidative stress, and cell apoptosis by inhibiting PPARγ ubiquitination and decreasing NADPH oxidase 4 (NOX4) expression." (PMID 39234245, 2024). "Others reported that NOX1 contributes to cardiomyocyte apoptosis and ventricular systolic dysfunction while NOX4 mediates renal tubular inflammation, apoptosis and mitochondrial dysfunction in sepsis." (PMID 38966542, 2024). "To further elucidate the action of the PKC/NOX4 pathway downstream of LPS-treated CD4+ T-cell-derived EVs in sepsis-induced lung injury, we directed our attention to CLP-induced sepsis in mice." (PMID 36959535, 2023). "This approach established the mechanism that T-cell-derived EVs exerted toxic effects in sepsis-induced lung injury through the DGKK/DAG/PKC/NOX4 pathway." (PMID 36959535, 2023). "RIPK3 upregulates NOX4 and promotes sepsis-induced AKI by inducing oxidative stress and mitochondrial dysfunction." (PMID 37627536, 2023). "This approach established the mechanism that T-cell-derived EVs carrying DGKK triggered alveolar epithelial cell apoptosis, oxidative stress, inflammation, and tissue damage in sepsis-induced lung injury through the DAG/PKC/NOX4 pathway." (PMID 36959535, 2023). "NOX4 (versus other NOX isoforms) was specifically involved in damage of the endothelial cell barrier in the lungs of a mouse model of CLP-induced sepsis." (PMID 36959535, 2023). "It has been reported that NOX4 knockdown decreased sepsis-induced ROS production, which was accompanied by an alleviation of ALI." (PMID 36451220, 2022). "In an LPS-induced septic model, Nox4-knockdown mice had decreased production of inflammatory mediators compared to mice overexpressing Nox4, data supporting the crucial role of Nox4 as a key component of the inflammatory response to sepsis." (PMID 33194001, 2020). "We measured oxidative stress, Nox2 and Nox4 gene expression and neuroinflammation in the hippocampus at six hours, twenty-four hours and five days post-sepsis." (PMID 24571599, 2014). "Sepsis-associated acute kidney injury (S-AKI) is characterized by complex pathological mechanisms, primarily driven by oxidative stress and inflammation, with NADPH oxidase 4 (NOX4) playing a critical role." (PMID 42014688, 2026). "Additionally, through the regulation of NOX4 expression, shikonin mitigated ROS production and improves sepsis-induced acute kidney injury in rats." (PMID 40520207, 2025).
Sepsis (continued). "In addition, new therapeutic approaches to inhibiting the NOX4/PKM2-dependent immunometabolism pathway have been reported as potential targets in the treatment of sepsis and inflammatory diseases." (PMID 37553596, 2023). "Therefore, this approach established the mechanism that T-cell-derived EVs exerted toxic effects in sepsis-induced lung injury through the DGKK/DAG/PKC/NOX4 pathway." (PMID 36959535, 2023). "Thus, the objective of this study was to explore the in vivo effects of echinacoside mediated by the SIRT1-regulated NOX4-Nrf2 axis on ALI induced by sepsis, as well as its in vitro effects on endothelial cells stimulated by LPS." (PMID 38001778, 2023). "Echoing these previous reports, our investigation demonstrated that NOX4 was specifically regulated by the DAG/PKC axis, and this DAG/PKC/NOX4 signaling played a supportive role in sepsis-induced lung injury, again indicating the therapeutic value of this signaling in the treatment of this disease." (PMID 36959535, 2023). "Taken together, all these data indicated that NOX4 in RTECs was induced by sepsis, and both genetic and pharmacological suppression of NOX4 could attenuate S-AKI." (PMID 37284448, 2023). "Although DAG, PKC, and NOX4 are involved in sepsis or ALI, the roles of DGK in sepsis-induced lung injury remain unknown." (PMID 36959535, 2023). "Consequently, the SIRT1-regulated NOX4-Nrf2 axis may represent a crucial target for echinacoside in the treatment of sepsis-induced acute lung injury." (PMID 38001778, 2023). "Serum apelin-13 could protect against sepsis-induced ALI by regulating NOX4-dependent ROS." (PMID 36959535, 2023). "Therefore, CD4+ T-cell-derived EVs might place unique demands on the DGK/DAG/PKC/NOX4 pathway to promote sepsis-induced lung injury in mice, including oxidative stress and inflammation." (PMID 36959535, 2023). "Overexpressing NOX4 can reverse this protective effect, revealing the key role of the “TRIM27-PPARγ-NOX4” ubiquitination axis in the lung injury of sepsis." (PMID 40643532, 2025). "EVs derived from lipopolysaccharide (LPS)-treated CD4+ T cells carrying DGKK induced oxidative stress and inflammation in alveolar epithelial A549 cells and sepsis-induced mice through PKC and NOX4, the downstream effectors of DGKK and DAG." (PMID 36959535, 2023). "In kidney tubular epithelial cells, receptor-interacting protein kinase-3 (RIPK3) facilitated oxidative stress, and mitochondrial dysfunction implicating NOX4 and RIPK3 upregulation was necessary for elevated mitochondrial translocation of NOX4 in sepsis." (PMID 37284448, 2023). "Mechanistically, EVs derived from LPS-treated CD4+ T cells carrying DGKK induced oxidative stress and inflammation in alveolar epithelial A549 cells and sepsis-induced mice through PKC and NOX4, the downstream effectors of DGKK and DAG." (PMID 36959535, 2023). "The ferroptosis-related genes (NOX4, HMOX1, POR, SAT1, etc.)were highly expressed in sepsis-induced cardiomyopathy model." (PMID 37035738, 2023). "Recent studies showed that NOX4 was characterized in the cardiovascular system, HMOX1 can be induced by sepsis, and POR was selected as the central gene of SIC." (PMID 37035738, 2023). "In the cultured alveolar epithelial A549 cell line and the lungs of a mouse model of CLP-induced sepsis, EVs derived from CD4+ T cells exerted toxic effects through DGKK and its stimulation on the DAG/PKC/NOX4 signaling pathways." (PMID 36959535, 2023). "Studies indicate that serum exosomes from sepsis patients induce oxidative stress, inflammation, and AECs injury via the Diacylglycerol Kinase (DGK)/Diacylglycerol (DAG)/Protein Kinase C (PKC)/NADPH Oxidase 4 (NOX4) pathway." (PMID 40842982, 2025). "Furthermore, a recent original study revealed that macrophagic extracellular vesicle CXCL2 can aggravate the progression of sepsis via recruiting and activating the neutrophil CXCR2/PKC/NOX4 axis." (PMID 40115159, 2024).
Sepsis (continued). "Western blot analysis revealed that in the LPS-induced sepsis model (Group 2), Nogo-A expression was significantly elevated, while the expression of proteins such as p-PERK, MFN1, NOX2, NOX4, NLRP3, p-STING, p-TBK1, and IL-1β also significantly increased, and SHP2 expression decreased." (PMID 39151100, 2024). "Therefore, this study aimed to investigate the effects of echinacoside on sepsis-induced acute lung injury and oxidative stress in mice and to explore the intricate regulatory mechanism of SIRT1 on NOX4." (PMID 38001778, 2023). "Real-time PCR analysis demonstrated that Nox2, but not Nox4 mRNA, was induced in the hippocampus 24 hours after sepsis, whereas oxidative stress was detected earlier at six hours, suggesting that NADPH oxidase activity is induced before the increase in gene expression." (PMID 24571599, 2014). "Interestingly, neither NOX2 nor NOX4 expression was affected by CLP or inflammatory mediators in the hearts and cardiomyocytes, raising questions about the role of NOX enzymes in sepsis-induced oxidative stress in the heart." (PMID 40801652, 2025).
acute kidney injury (29 papers, 2016 to 2026). Sudden and sustained deterioration of the kidney function characterized by decreased glomerular filtration rate, increased serum creatinine or oliguria. "Recent work highlights melittin’s capacity to attenuate NOX4-mediated oxidative stress and activate Nrf2-associated pathways in renal tissue, offering protection against acute kidney injury." (PMID 41301702, 2025). "This scenario was described in a model of acute kidney injury where Nox4 deficiency resulted in augmented tubular cell apoptosis due to a decline in the antioxidant and antiapoptotic response." (PMID 33059312, 2020). "Upregulation of renal NOX2 or NOX4 orboth have been implicated in acute kidney injury (AKI) and CKD." (PMID 30907266, 2019). "Recently, emerging evidence has revealed that nicotinamide adenine dinucleotide phosphate (NADPH) oxidase 4 (NOX4) is implicated in various renal diseases, while its role and modulation in septic acute kidney injury (S-AKI) remains largely unknown." (PMID 37284448, 2023). "HSP increased Nrf2 signalling, SIRT6, NQO1, HO-1 expression, down-regulated SCr, blood urea nitrogen (BUN), MDA, MPO, GSH, SOD, NOX4 expression level, thereby relieving cisplatin-induced acute kidney injury." (PMID 35128104, 2022). "NOX4 contributes to redox processes involved in diabetic nephropathy, acute kidney injury (AKI), and other renal diseases by activating multiple signaling pathways." (PMID 35011880, 2021). "We show that this Nox4‐regulated pathway robustly enhances cell survival and has a physiologic role in heart ischemia–reperfusion and acute kidney injury." (PMID 26742780, 2016). "To investigate the function of NOX4 in acute kidney injury (AKI), we established a mouse model of glycerol-induced AKI, which is a commonly used AKI animal model to imitate the pathological process of RIAKI in humans." (PMID 41154471, 2025). "Nox4 (NADPH oxidase 4) in relation to acute kidney injury (AKI) appears to have a complex and controversial role." (PMID 38360882, 2024). "Furthermore, deletion of NOX4 in human proximal tubular epithelial cells (HK‐2 cells) suppressed ROS production, proinflammatory marker expression and cellular apoptosis in models of hypoxia‐, colistin‐ and contrast‐induced acute kidney injury (AKI) in vitro." (PMID 36658776, 2023). "Thus, we propose that hypoxia upregulates the expression of Nox4 via the TGF-β/Smad pathway and increases ROS production and therapies targeting Nox4 may be effective against hypoxia-induced acute kidney injury." (PMID 31318905, 2019). "Moreover, silencing Nox4, but not Nox2, removed the inhibitory effect of PA on cisplatin-induced renal injury, indicating that Nox4 may play a pivotal role in mediating the protective effect of PA in cisplatin-induced acute kidney injury." (PMID 27999546, 2016).